RNF43 (ring finger protein 43)
Diseases named in the same sentence as RNF43 in open-access papers (continued):
Sharing a sentence is not in itself a finding about the gene and the disease.
pancreatic cancer (continued). "Since Wnt‐addicted cells are substantially more sensitive to PORCN inhibitors when grown in suspension, the screen was performed in the Wnt‐addicted RNF43‐mutant pancreatic cancer cell line HPAF‐II using soft agar colony formation as the readout." (PMID 33660437, 2021). "Although the 1503 Wnt-regulated lncRNAs were discovered in the orthotopic RNF43-mutant pancreatic cancer xenograft model, many of them were also dysregulated in different types of cancers in TCGA." (PMID 33092630, 2020). "To specifically identify the lncRNAs that play functional roles in the pathogenesis of RNF43-mutant pancreatic cancer in vivo, we performed CRISPRi screens." (PMID 33092630, 2020). "Using these stringent criteria, we identified a set of 3633 lncRNAs in an orthotopic RNF43-mutant pancreatic cancer model." (PMID 33092630, 2020). "These genetic changes, together with others (i.e. K108E, R117H, E170K), are described in cases of large intestine and pancreatic cancers (COSMIC database: cancer.sanger.ac.uk), suggesting RNF43 loss-of-function." (PMID 32527265, 2020). "Taken together, we identified 1503 lncRNAs whose expression is regulated either directly or indirectly by Wnt signaling in vivo in an RNF43-mutant pancreatic cancer." (PMID 33092630, 2020). "In xenograft models, WNT974 inhibits proliferation and induces differentiation of RNF43 mutant pancreatic tumors." (PMID 27338477, 2016). "Treatment with a Porcupine inhibitor reduces growth of RNF43 mutant pancreatic cancer cell lines, where proliferation is dependent on endogenous Wnt signalling." (PMID 27661107, 2016). "A genome-wide CRISPR screening approach identified a druggable Wnt-FZD5 signaling circuit as a critical vulnerability specific to RNF43-mutant pancreatic tumors, revealing a potential therapeutic strategy for this genetically defined subset of pancreatic cancers." (PMID 39936971, 2025). "In pancreatic cancer cell lines with RNF43 loss-of-function mutation, the frizzled level was no longer inhibited." (PMID 37848933, 2023). "Small molecule PORCN inhibitors that block the biogenesis of Wnt ligands as well as antibodies that block Wnt function have been shown to inhibit tumor growth in preclinical models of RNF43-mutant pancreatic cancers, and several have advanced into clinical trials." (PMID 35536676, 2022). "We then asked whether the mutation of these Wnt pathway genes was responsible for PORCN inhibitor resistance in RNF43-mutant pancreatic cancers." (PMID 35536676, 2022). "Intrinsic resistance to PORCN inhibitors in some RNF43-mutant pancreatic cancers." (PMID 35536676, 2022). "Moreover, in preclinical studies, several pancreatic cancer cell lines with confirmed RNF43 inactivation were identified that were resistant to PORCN inhibition in cell culture." (PMID 35536676, 2022). "Loss of p300 mediated Wnt/β-catenin–independent tumor growth in RNF43-mutant pancreatic cancer." (PMID 35536676, 2022). "We further investigated whether reexpressing WT EP300 in the existing RNF43/EP300-mutant pancreatic cancer cell line was able to rescue the Wnt dependency." (PMID 35536676, 2022). "As expected, RNF43-mutant pancreatic cancer xenografts remained dependent on Wnt ligand." (PMID 35358569, 2022). "Notably, GATA6 protein abundance was also markedly reduced in the RNF43/EP300-mutant pancreatic cancer cell lines, and reexpressing p300 in EP300-mutant PL45 cells upregulated GATA6 expression." (PMID 35536676, 2022). "On the other hand, Panc 08.13, a pancreatic cancer cell line with no RNF43 mutation, has low abundance of Frizzleds on the cell surface and hence has low Wnt signaling." (PMID 33660437, 2021). "Similarly, WNT7B-FZD5 signaling promotes RNF43-mutant pancreatic cancer cell proliferation and growth." (PMID 33618713, 2021).
pancreatic cancer (continued). "Mutation in RNF43 is more frequent than ZNRF3 and its associated repercussions are pancreatic tumors called intraductal papillary mucinous neoplasm and mucinous cystic neoplasm, colorectal adenocarcinomas, pancreatic cancer, gastric cancer, mucinous ovarian carcinoma, and endometrial carcinomas." (PMID 34535145, 2021). "In pancreatic cancer in which RNF43 was mutated at relative high frequency except that no G659Vfs*41 mutation was identified, none of the tumors had low MLH1 expression." (PMID 31811196, 2019). "Early findings described RNF43 as an oncoprotein highly expressed in colorectal tumors, whereas more recent research has supported its function as a tumor suppressor protein in pancreatic cancer, ovary cancer, hepatocellular cancer, and GC." (PMID 28446252, 2017). "Furthermore, compound 11 blocked WNT-3A-induced LGR5 gene expression in human primary hepatocyte spheroids and reduced the viability of RNF43-mutated but not RNF43-wildtype pancreatic cancer cells." (PMID 40992662, 2025). "Moreover, FZD5 has been identified as a dominant FZD receptor in RNF43-mutant pancreatic cancer cells and may be a therapeutic index." (PMID 33291655, 2020). "In colon, endometrial, and stomach cancers, G659Vfs*41 accounted for 40% (23/81), 53% (42/79), and 48% (25/77), respectively, of all RNF43 mutations, whereas not a single G659Vfs*41 mutation (0/13) was found in pancreatic cancer (p < 0.05 vs any of the other three cancer types, Fisher’s exact test)." (PMID 31811196, 2019). "These include the colorectal, gastric, ovarian and pancreatic cancers that harbour inactivating mutations in RNF43 (refs 65, 66, 67, 68, 69, 70), a negative Wnt feedback regulator that promotes degradation of the Wnt co-receptors Frizzled and LRP6 (refs 70, 71, 72)." (PMID 27138857, 2016). "Collectively, the research reveals a novel mechanism by which RNF43 inhibits B‐RAF/MEK signaling to suppress tumor growth and provide a new strategy for the treatment of RNF43‐inactivated pancreatic cancer." (PMID 38225722, 2024). "In this study, we identified B‐RAF as an in vivo substrate of RNF43 and elucidated the role of RNF43 in modulating the activation of the MEK/ERK signaling pathway through B‐RAF in pancreatic cancer cells." (PMID 38225722, 2024). "Depletion of RNF43 E3 ligase remodeled the TIME and facilitated Kras-induced oncogenesis in pancreatic cancer." (PMID 36733484, 2023). "Similar to ARID1A, the inactivation of RNF43 in combination with KRAS activation in the pancreas of mice significantly increased the incidence of high‐grade cystic lesions and pancreatic cancer." (PMID 36999792, 2023). "Here, to identify mechanisms that confer resistance to upstream Wnt pathway inhibitors in RNF43-mutant pancreatic cancers, we performed in vivo CRISPR screens during PORCN inhibitor therapy in mice bearing RNF43-mutant pancreatic tumor xenografts." (PMID 35536676, 2022). "Coexistence of mutated RNF43 and KRAS in PDAC also supports a collaboration between RNF43 and KRAS in the development of human pancreatic cancer." (PMID 35229994, 2022). "In addition, we used the GDSC database analysis to prove that the mTOR inhibitor (GSK2126458) is very sensitive to pancreatic cancer cell lines, especially for EWSR1.FLI2 and RNF43 mutant." (PMID 34461940, 2021). "The strength of this negative feedback regulation is demonstrated by the finding that the knockdown of β?-catenin in a pancreatic cancer line with wild-type ZNRF3 and RNF43 strongly increases the cell surface level of FZD, most likely through down-regulation of endogenous RNF43 and ZNRF3." (PMID 27338477, 2016).
pancreatic cancer (continued). "Since the gene panel did not include GNAS, VHL, or RNF43, we could not rule out the possibility of IPMN-derived pancreatic cancer associated with these genes." (PMID 36980386, 2023). "However, these factors are not related to the Wnt-independency phenotype in RNF43-mutant pancreatic cancer, since sgRNAs targeting KDM6A or negative regulators of GLI2 or YAP1, i.e., PTCH1, LATS1, and SAV1, were not enriched in ETC-159 versus vehicle-treated tumors in our initial CRISPR screens." (PMID 35536676, 2022). "However, these negative regulators of the Wnt/β-catenin pathway were neither mutated nor silenced in the existing PORCN inhibitor–resistant RNF43-mutant pancreatic cancer cell lines based on genome, exome, and/or transcriptome sequencing results from public databases." (PMID 35536676, 2022). "While YAP signaling clearly supported the proliferation of RNF43-mutant pancreatic cancer, the sgRNAs targeting YAP suppressors SAV1 or LATS1 were not further enriched by ETC-159 treatment, suggesting that YAP activation could not bypass Wnt dependency in RNF43-mutant pancreatic cancer." (PMID 35536676, 2022).
gastric cancer (36 papers, 2016 to 2025). A primary or metastatic malignant neoplasm involving the stomach. "A similar difference was observed in stomach cancer, which also displayed a high frequency of the RNF43 G659Vfs*41 mutation." (PMID 38260423, 2024). "Dysregulated Wnt signaling affects almost 50% of gastric cancers, with the most commonly mutated genes being RNF43, AXIN1/2, CTNNB1, and APC." (PMID 39191487, 2024). "The same G659 frameshift mutation accounts for approximately 25% of RNF43 mutations in gastric cancer." (PMID 37048063, 2023). "While we find that high expression of RSPO3 in the stroma can result from injury and infection, elevated R-spondin signaling can also occur as a result of a mutational event in genes such as RNF43, which is observed in a subset of patients with gastric cancer." (PMID 36099044, 2022). "RNF43 attenuated tumor growth and the stem cell-like phenotype by inhibiting the canonical Wnt/β-catenin pathway in gastric cancer, and loss of RNF43 was closely associated with poorer prognosis." (PMID 35568845, 2022). "Loss of RNF43 function weakens the DNA damage response, leading to resistance to radiotherapy and chemotherapy in gastric cancer." (PMID 36439494, 2022). "The loss of RNF43 is associated with distant metastasis and a poor prognosis for gastric cancer patients." (PMID 33825941, 2021). "In another study, mutations of RNF43 were found in 0–17% samples, while other members of Wnt signaling in gastric cancer include CTNNB1 (3.3–9.1%) and APC (3.3–14.9%)." (PMID 34488905, 2021). "Most recently, mutational inactivation of RNF43 in gastric cancers was found to induce resistance to DNA damage." (PMID 33660437, 2021). "RNF43 mutations have been found to accompany the transition from adenoma to dysplasia and gastric cancer." (PMID 33825941, 2021). "The HAP1 cell line was used to determine how the loss-of-function of RNF43 or PWWP2B correlate with gastric cancer." (PMID 34149925, 2021). "For example, 37% of APC-mutant gastric cancers have mutation in RNF43, suggesting a compound activation of Wnt signaling in the same tumor." (PMID 34552611, 2021). "In the present study, we combined the presence of mutated Rnf43 with chronic H. pylori infection, since the latter is a major risk factor for the development of gastric cancer." (PMID 30884828, 2019). "RNF43 expression was shown to be lost in poorly differentiated gastric cancers, while mutations were concentrated in gastric carcinomas adjacent to adenomas, indicating an important role for RNF43 in the transition from adenoma to carcinoma." (PMID 30884828, 2019). "Whole genome sequencing also revealed that the ubiquitinase RNF43 is frequently mutated and subsequently downregulated in gastric cancer." (PMID 31248166, 2019). "Of note, expression of RNF43 in non-RNF43-mutated colon tumors was much higher than those in endometrial and stomach cancers." (PMID 31811196, 2019). "Loss-of-function mutations of the Wnt signaling inhibitor RNF43 have also been confirmed in three gastric cancer cell lines." (PMID 31248166, 2019). "Colon, endometrial, pancreatic, and stomach cancers showed the highest incidences of all RNF43 mutations with frequencies of 10.9%, 15.2%, 7.3%, and 11.9%, respectively." (PMID 31811196, 2019). "Interestingly, RNF43 mutations in gastric cancer, endometrial cancer, and CRC are associated with microsatellite instable tumours." (PMID 37048063, 2023). "Indeed, RNF43 and ZNRF3 (which ubiquitinate and stabilise WNT receptors) are found mutated in gastric cancer (RNF43 mutations are frequent, while ZNRF3 mutations are rare)." (PMID 35408991, 2022). "However, analysis of RNF43 mutations during progression of tumors from low grade to high grade dysplasia and early gastric cancer revealed that mutations in RNF43 occurred at the stage of high grade dysplasia and early gastric tumors." (PMID 30884828, 2019).
gastric cancer (continued). "Furthermore, more than 80% of gastric cancer samples showed loss of heterozygosity at the RNF43 locus, which is an indicator for the loss of tumor suppressor genes." (PMID 31248166, 2019). "Mutation in UVRAG and RNF43 is liable for the advancement of various cancers, such as gastric cancer, colorectal, and endometrial cancers, but variation in these genes may be linked with the advancement of BRCA." (PMID 31311202, 2019). "The E3 ubiquitin ligase ring finger protein 43 (RNF43) is frequently mutated in gastric tumors and loss of RNF43 expression was suggested to be one of the key events during the transition from adenoma to gastric carcinoma." (PMID 30884828, 2019). "In hypermutated gastric carcinomas, 33% of tumors carried a RNF43 mutation." (PMID 31248166, 2019). "Indeed, the MSI subtype of gastric cancer has a nearly 10-fold higher mutation frequency in RNF43 than that of the microsatellite stable (MSS) subtype (54.6% versus 4.8%)." (PMID 27338477, 2016). "This may explain why cancers with a deficiency in DNA mismatch repair, such as colon cancer, endometrial cancer and gastric cancer, have frequent RNF43 mutations." (PMID 27338477, 2016). "In addition, 34 gastric cancer patients carried germline RNF43 mutations." (PMID 34149925, 2021). "In addition, RNF43 mutations occurred in 35.2% of early gastric cancer adenomas." (PMID 31248166, 2019). "For instance, it has been found that RNF43 can attenuate the stemness of gastric cancer stem-like cells by inhibiting the Wnt/β-catenin pathway and impairing the chemoresistance in vitro." (PMID 37848933, 2023). "At the 3-year follow-up 11 of 34 patients (32%) had gastric cancer relapse (11 of 11 [100%] in the low RNF43 and low PWWP2B expression group)." (PMID 34149925, 2021). "Recent studies found that depletion of RNF43 enhanced tumor growth in GI cancers and conferred resistance to DNA-damage-inducing chemotherapies and γ-radiation in gastric cancer cells." (PMID 34594355, 2021). "RNF43 is a tumor suppressor gene in mucinous ovarian cancers, mucinous pancreatic precancerous cysts, and gastric cancer 11-15." (PMID 34149925, 2021). "We specifically chose to study RNF43 because it inhibits gastric cancer-related Wnt/β-catenin signaling by interacting with Wnt receptors." (PMID 34149925, 2021). "Using a gastric cancer cohort, we retrospectively evaluated the relationship between RNF43 and PWWP2B expression levels and clinical characteristics." (PMID 34149925, 2021). "We to try select effective drugs in recurrence gastric cancer patients with low RNF43 and low PWWP2B expression, by using HAP1 cell line." (PMID 34149925, 2021). "In fact, absolute mRNA levels of RNF43 in RNF43-G659Vfs*41colon cancer tumors was nearly identical to those in endometrial and stomach cancer." (PMID 31811196, 2019). "Gastric cancers with low expression levels of RNF43 resulted in the worst prognosis for the cancer patient." (PMID 31248166, 2019). "Given its antagonistic relationship with leucine-rich repeat-containing G-protein-coupled receptor 5 (Lgr5), one of the gastric cancer stem cell markers, investigation of the potential role of RNF43 in gastric stem cancer cells is necessary." (PMID 28446252, 2017). "Functional experiments including tumorsphere formation, chemotherapy resistance, surface marker detection, and tumor xenograft assay were performed to measure stem-like properties in gastric cancer stem-like cells after RNF43 overexpression." (PMID 28446252, 2017). "RNF43 loss was significantly associated with TNM stage, distant metastasis, and Lauren classification, and predicted worse prognosis in gastric cancer patients." (PMID 28446252, 2017). "Overexpression of RNF43 in gastric cancer cells impaired their stem-like properties, including sphere formation ability, chemoresistance in vitro, and tumorigenicity in vivo." (PMID 28446252, 2017).